CGAS (cyclic GMP-AMP synthase)
Diseases named in the same sentence as CGAS in open-access papers (continued):
Sharing a sentence is not in itself a finding about the gene and the disease.
tumor (continued). "cGAS-derived cGAMP in tumor cells diffuses to neighboring non-cancerous cells through gap-junction channels to activate STING, contributing to the recruitment of protective tumor-infiltrating immune cells such as NK cells." (PMID 34659260, 2021). "Several reports have suggested the importance of the cGAS-STING axis in antitumor responses, rather than other nucleic acid-sensing receptor-mediated pathways, by bridging innate immune responses and tumor-specific T cell responses via the production of type I IFNs." (PMID 33633744, 2020). "Furthermore, our results imply that the current cGAS or STING ligands under development for treating or serving as adjuvants in certain cancers will likely not work in tumor types defective in STAG2 and the cytosolic DNA-sensing pathway." (PMID 29662124, 2018). "Interestingly, cGAS/STING can lead to the activation of non-canonical NF-κB signaling without altering IFN signaling, indicating that cancer cells can eschew type I IFN signaling while benefiting from cGAS/STING-induced pro-tumor inflammation." (PMID 39544936, 2024). "This is in contrast to our observations where HER2 amplification is associated with an inflammatory phenotype characterised by activation of the cGAS-STING pathway and we observe that HER2/EGFR blockade may be immunosuppressive rather than increasing tumour immune cell populations." (PMID 39395265, 2024). "As previously reported, Ifnb1 could be induced in vitro by a cGAS-STING agonist, yet in vivo it was more highly expressed in CD45+ cells than in tumor cells; by contrast, other IFNs, particularly Ifne, were not induced by these stimuli in vitro and showed preferential expression in tumor cells." (PMID 36344707, 2022). "Importantly, the growth of tumor cells and antigen-specific CTL activation were not altered in either Mn-insufficient or Mn2+-administrated Tmem173−⁄− mice, confirming the essential role of cGAS-STING in Mn2+-mediated host immune responses against tumor cells." (PMID 32839553, 2020). "Indeed, unlike free 2′3′‐cGAMP, LL‐37‐2′3′‐cGAMP‐induced ISRE reporter activity was not affected by tumor‐derived exosomes concentration in presence STF‐1623, which suggests further that tumor‐derived exosomes did not assist LL‐37‐2′3′‐cGAMP to activate cGAS‐STING pathway." (PMID 38498770, 2024). "It is now widely accepted that the cGAS-STING signaling cascade may rely primarily on synthetic interferons (IFNs) to exert anti-tumor effects, but recent studies have found that it also has significant regulatory effects on non-immune pathways and influences tumor progression." (PMID 37965570, 2023).
cancer (784 papers, 2016 to 2026). A tumor composed of atypical neoplastic, often pleomorphic cells that invade other tissues. "Chromosomal instability (CIN), a hallmark of cancer, leads to the release of cytosolic double-stranded DNA (dsDNA), which activates the cGAS-STING pathway and its downstream immune signaling." (PMID 41706744, 2026). "Cisplatin-induced DNA damage promotes a cGAS-STING–dependent senescence program in cancer-associated fibroblasts (CAFs), resulting in the secretion of CCL5, a key senescence-associated secretory phenotype factor." (PMID 41152972, 2025). "In cancers with a high mutational burden, cGAS-STING activation enhances immune recognition, making it a potential therapeutic target." (PMID 40052963, 2025). "The susceptibility of STING-deficient mice to certain cancers, including breast and pancreatic tumors, highlights the pivotal role of the cGAS-STING pathway in regulating PANoptosis." (PMID 40008397, 2025). "Since autophagy has been considered as a double-edged sword, triggering cancer progression in advanced stages, the underlying role of cGAS–STING in inducing autophagy should be studied in depth." (PMID 41378291, 2025). "Within cancer cells, the engagement of the cGAS/STING pathway is often linked to immune evasion and resistance to therapeutic agents, where varying levels of cGAS expression can affect how tumors respond to immune checkpoint inhibitors." (PMID 40008397, 2025). "Elevated cytoplasmic DNA levels in cancer cells are a hallmark, contributing to a persistent basal activation of the cGAS/STING pathway, which can potentially be induced." (PMID 38817608, 2024). "Several clinical and preclinical studies have linked an active cGAS-STING pathway to superior positive outcomes for cancer treatment with chemotherapy, radiotherapy, and immunotherapy." (PMID 40012911, 2024). "Previous studies have demonstrated that cytoplasmic dsDNA in cancer cells caused by DNA virus infection, genomic DNA damage or mitochondrial DNA leakage can be recognized by cGAS, which can activate cGAS." (PMID 38566036, 2024). "Most of our knowledge about the role of interferon signaling in response to IR-induced DNA damage comes from studies in cancers where it is often linked to cGAS/STING signaling." (PMID 38352597, 2024). "Lan team found that cGAS-deficient untransformed cancer cells exhibited uncontrolled DNA replication, leading to genomic instability and excessive proliferation." (PMID 38515746, 2024). "Cancer cells utilize this mechanism of TREX1 action to inhibit the activation of cGAS-STING caused by DNA damage and thus realize immune escape." (PMID 38495488, 2024). "Further research is crucial to define the precise role of cGAS-STING in oncology and to elucidate both its distinct benefits and potential drawbacks associated with targeting the cGAS-STING pathway in cancer therapeutics." (PMID 38817608, 2024). "Chromosomal instability (CIN) is a hallmark of cancer as well as a primary source of cytosolic dsDNA and it promotes the activation of cGAS-STING." (PMID 38510490, 2024). "Significantly, the TME has garnered substantial attention in cancer therapy research due to the potential anti-cancer effects associated with activating the cGAS-STING pathway in the TME." (PMID 37448962, 2023). "Around 12% of all human tumors are caused by such viruses, and the cGAS-STING pathway should play a prominent role as an anti-cancer guardian against at least some of these viruses." (PMID 38139802, 2023). "Although this has been demonstrated in several cancer cell lines, the genes for either cGAS or STING are rarely mutated in cancers." (PMID 37534795, 2023). "Cancer immunotherapy can be improved by activating the cGAS-STING pathway, which has been linked to the inhibition of ATM, ATR, CHK1, and PARP." (PMID 36831197, 2023).
cancer (continued). "KSHV and hepatitis B, which are also associated with cancer, have been found to interfere with the cGAS-STING pathway by expressing interferon regulatory factor 1, envelope protein ORF52, and viral polymerase binding, according to studies." (PMID 37781382, 2023). "Our findings present what is, to our knowledge, the first evidence for POLQ inhibition activating cGAS-STING signaling in HR-deficient cancer." (PMID 36976649, 2023). "We further highlight the diseases where they are important and detail how this change in perspective can be applied to vaccine design, cancer immunotherapies and treatment of cGAS-STING associated disease." (PMID 37287967, 2023). "Specifically, in TNBCs, overactive cGAS–IL-6–IL-6R signaling is linked to decreased immune-cell survival and increased cancer-cell growth." (PMID 38139802, 2023). "It has been proposed that chromosome segregation defects in chromosomally unstable cancer cells or upon treatment of cancer cells with Taxanes can cause formation of cGAS-positive micronuclei and activation of proinflammatory pathways." (PMID 36960066, 2023). "Chromosomal instability in cancer is linked to endoplasmic reticulum stress signalling, immune suppression and metastasis, which is mediated by the cGAS–STING pathway, suppression of which can reduce metastasis." (PMID 37612508, 2023). "The DNA damage caused by traditional cancer treatments such as radiation and chemotherapy is one of the main ways in which cancer cells are eradicated, and is increasingly being linked with cGAS-STING activation." (PMID 37627155, 2023). "Herein, we review the traditional cancer therapies that have been linked with cGAS-STING activation, highlighting their targets with respect to their role and function in the DNA damage response." (PMID 37627155, 2023). "For example, in BRCA1-mutated cancer cells, the killing effect of Olaparib treatment is observed in association with cGAS/STING pathway activation." (PMID 36706121, 2023). "Chromosomal instability (CIN)—another hallmark of cancer—occurs following chromosomal segregation errors during mitosis and can also activate the cGAS/STING pathway in cancer cells." (PMID 36387071, 2022). "Along with this context, genome instability, a hallmark of cancer cells, generates cytosolic dsDNA that activates the cGAS-STING pathway and induces chronic inflammation." (PMID 35741087, 2022). "Chromosomal instability (CIN) is a hallmark of cancer, but also leads to an accumulation of cytosolic DNA that in turn results in increased cGAS-STING signaling." (PMID 36923311, 2022). "In another study, inhibition of Ataxia telangiectasia mutated (ATM) enhanced cancer immunotherapy by promoting mitochondrial DNA leakage and cGAS/STING activation." (PMID 36221123, 2022). "Several studies have indicated that cancer-associated genomic instability can also modulate cGAS/STING signals." (PMID 35046953, 2021). "The genetic instability of cancer cells causes the presence of cytosolic DNA, which plays the main role in the activation of the cGAS-STING pathway." (PMID 34858438, 2021). "Cyclic GMP–AMP synthase (cGAS) detects the cytosolic DNA caused by DDR deficiency in cancers and activates stimulator of interferon genes (STING), which triggers interferons (IFNs) signaling and antitumor immunity." (PMID 33791310, 2021). "Recent evidence has revealed the close association of the cGAS-STING pathway with cancer development." (PMID 32854711, 2020). "Cancer cells show frequent loss or epigenetic silencing of the cytosolic DNA sensor cGAS and/or STING to promote immune evasion." (PMID 32649682, 2020). "Using RNA-Seq analysis across several cancer genome databases, it was shown that cGAS and STING were specifically associated with an increase in pro-inflammatory gene expression in human cancers." (PMID 32774773, 2020).
cancer (continued). "There was substantial increase in interferon response genes, which along with TMEM173 mRNA expression, suggested PARP inhibition activated the cGAS–cGAMP–STING pathway in HR-deficient cancers." (PMID 32471999, 2020). "Cancer cells deficient in cGAS or STING were resistant to this combination therapy, suggesting that CHK1 inhibitors enhance antitumor immunity by activating the cancer cell’s intrinsic cGAS-STING pathway." (PMID 32541866, 2020). "In various cancer cell lines, cGAS, STING, TBK1, and IRF3 are mutated frequently and their decreased expressions are also related to the high level of methylation." (PMID 32411126, 2020). "Surviving cancer cells tend to harbor deficiencies in the cGAS-STING pathway under selective pressure." (PMID 32571374, 2020). "In agreement with the concept that TBK1 loss affects antitumor immunity, studies by the Cantley and Barbie groups have reported that immune evasion and metastatic behavior are associated with the cGAS/STING/TBK1 innate immune pathway in cancer cells." (PMID 31681587, 2019). "As the consequence of selective pressure, surviving cancer cells tend to harbor deficiencies in cGAS-STING pathway." (PMID 30935414, 2019). "Activation of alternative lengthening of telomeres (ALT) plays a role in some cancers and is associated with the cytosolic localization of telomeric repeats and cGAS-STING activation." (PMID 30482235, 2018). "Apart from its role in protecting the host from a variety of pathogenic attacks, cGAS/STING pathway also plays a crucial role in cancer." (PMID 29156566, 2017). "In cancer, R-loops have been associated with replication stress, and a number of studies have showed that cytosolic ssDNA fragments can arise from this situation, causing the induction of interferon and inflammatory responses in a cGAS-STING-dependent manner." (PMID 41188872, 2025). "These fragments cause cancer cells to produce an IFN-I signal that depends on cGAS." (PMID 41007720, 2025). "We hypothesized that the cancer immunogenicity of ARID1A-deficient cells was increased for dendritic cell recognition to attract infiltrating immune cells via the ssDNA/CHK1/cGAS/STING pathway." (PMID 40750787, 2025). "Whether long-term inhibition of the cGAS/STING pathway could potentially increase susceptibility to infection or cancer is unknown." (PMID 39295301, 2024). "Indeed, PRMT9 inhibition or expression of XRN2-R946K in AML cells promoted R-loop formation and ATR signaling, which underlies cGAS activation in cancer cells." (PMID 38413714, 2024). "cGAS interacts with replication fork proteins in a DNA binding-dependent manner in the nucleus to slow replication fork movement and reduce cell susceptibility to DNA damage, indicating that cGAS is an attractive target for exploiting genomic instability of cancer cells." (PMID 38515746, 2024). "On the contrary, cGAS-deficient cancer cells are more sensitive to radiation and chemotherapy." (PMID 39247812, 2024). "Given the involvement of POLE mutants in most tumors, further exploration is warranted to determine whether POLE mutations also activate the cGAS-STING pathway in other cancer models." (PMID 38238314, 2024). "Furthermore, in line with the strong association between inflammation and cancer, cGAS activation by MN has been linked to cancer progression, promoting cellular invasion and metastasis." (PMID 39120648, 2024). "In the past few years, cGAS has been implicated in immune response mechanisms to cancer." (PMID 38473384, 2024). "Based on the evidence presented above, cGAS-STING is inextricably linked to cancer." (PMID 36936940, 2023). "Together, our data suggest that the IFN-I response could be associated with constitutive activation of the DNA sensor cGAS by recognising nuclear DNA in the cytosol of metastatic and aggressive cancer cells." (PMID 36882786, 2023).
cancer (continued). "Consequently, cGAS-STING signaling places neoplastic cells at risk of initiating anticancer immunity by cGAS sensing of cytoplasmic dsDNA fragments in cancer cells exhibiting genomic instability." (PMID 37079538, 2023). "These antagonistic effects of cell-intrinsic inflammatory signaling might explain why cancers rarely show loss of function mutations of cGAS and STING, but rather epigenetic silencing." (PMID 37561163, 2023). "cGAS serves as a node for regulating diverse regulatory functions in response to various cellular processes including autophagy, apoptosis, inflammation, tissue fibrosis, pathogenic infections (bacteria or virus), tumorigenesis, and cancer." (PMID 36139387, 2022). "Unsurprisingly, cGAS deficient (cGAS-/-) mice have been used as susceptible cancer models." (PMID 36142859, 2022). "Despite the deficiency in cGAS, S. cerevisiae still attenuated cancers, implying a cGAS-independent mechanism that might be correlated with WGP-altered macrophage activities." (PMID 36142859, 2022). "However, we observed that RAD51 overexpression in normal as well as cancer cells was associated with increased DNA breaks and genomic instability but reduced cGAS expression." (PMID 36428789, 2022). "However, in reality spontaneous production of type I interferons is rare in human cancer, and loss-of-function mutations in the cGAS and STING genes are also scarce in human cancers." (PMID 35992877, 2022). "However, in the future, after obtaining sEVs using TSU, we need to evaluate if EV-DNA association with cGAS-STING plays an essential role in cancer." (PMID 35565197, 2022). "In the present study, we performed a pan-cancer analysis using the cGAS-STING-related risk score." (PMID 35983076, 2022). "In cancer cells, the cGAS-STING signaling axis is linked with remodeling of the immunosuppressive TME, and, via the resulting type 1 IFNs, upregulation of suppressed major histocompatibility complex (MHC) class I expression necessary for CTL recognition and targeting." (PMID 36559204, 2022). "Moreover, up-regulation of cGAS-STING activation markers is observed in HR-deficient as compared to HR-proficient cancer cells." (PMID 33808562, 2021). "Furthermore, cancer cells can survive and evade immune responses through harboring deficiencies in the cGAS-STING pathway." (PMID 34858438, 2021). "Thus via acting as a decelerator of DNA replication forks, the nuclear cGAS suppresses replication-associated DNA damage that can efficiently target to exploit genomic instability of cancer cells." (PMID 33643304, 2020). "Importantly, the cGAS-STING pathway has also been robustly linked to the induction of cancer cell senescence, thereby mediating the oncosuppressive effects." (PMID 32571374, 2020). "However, large scale cancer sequencing datasets, such as The Cancer Genome Atlas (TCGA), reveal that genes encoding cGAS or STING are rarely mutated when assessing more than 10,000 tumors." (PMID 31658669, 2019). "This previously unknown role of cGAS has implications for understanding its involvement in genome instability‐associated disorders including cancer." (PMID 31544964, 2019). "Therefore, cGAS-STING agonist is an ideal sensitizer for cancer immunotherapy and decreases the risk of drug resistance." (PMID 30935414, 2019). "Interestingly, loss of the NE is observed during cancer cell migration and leads to cGAS accumulation at the rupture sites." (PMID 29911071, 2018). "Selection for loss of cGAS/STING signalling during cancer progression might help explain patient-to-patient variation, and suggests biomarkers for predicting high responders." (PMID 29142107, 2017). "Thus, cancer is rare in armadillos, and possibly pangolins, which may be related to the loss of the evolutionary CGAS and STING1 genes." (PMID 40463121, 2025).